INPP4B (inositol polyphosphate-4-phosphatase type II B)
Diseases named in the same sentence as INPP4B in open-access papers (continued):
Sharing a sentence is not in itself a finding about the gene and the disease.
tumor (continued). "In cancer, INPP4A and INPP4B are considered to act as tumor suppressors by inhibiting the PI3K/AKT signaling pathway in several tumor types including breast, ovary, lung, pancreatic, melanoma, and esophageal cancer." (PMID 32296634, 2020). "Its function as a tumor suppressor was shown through decreased proliferation and Akt activation upon restoration of INPP4B expression in the ER-negative breast cancer cell line, MDA-MB-231." (PMID 32085745, 2020). "Proteins that contribute most strongly to the proteotype-based classification include INPP4B, CDK1, and ERBB2 and are associated with estrogen receptor (ER) status, tumor grade status, and HER2 status." (PMID 31315058, 2019). "Inositol Polyphosphate 4-Phosphatase, Type II (INPP4B) is a tumour suppressor in breast, ovarian, prostate, thyroid and other cancers, attributed to its ability to reduce oncogenic Akt-signaling." (PMID 31695845, 2019). "The three key proteins identified by our decision tree are strongly associated with important clinical parameters, namely ER status (INPP4B), tumor grade (CDK1), and HER2 status (ERBB2)." (PMID 31315058, 2019). "Several studies have subsequently validated a tumour suppressor role for INPP4B in breast, ovarian, skin, and prostate cancer among others." (PMID 31695845, 2019). "The most common mutation detected in primary tumor tissues was PIK3CA (6 patients, 37.5%), followed by ERBB2, mTOR and INPP4B (5 patients for each one, 31.25%)." (PMID 30167082, 2018). "In breast and other epithelial cancers, INPP4B has been predicted to be a tumor suppressor that blocks AKT activation." (PMID 29343273, 2018). "The inositol polyphosphate-4-phosphatase type II (INPP4B) has been mostly proposed to act as a tumor suppressor whose expression is frequently dysregulated in numerous human cancers." (PMID 29952716, 2018). "The overexpression of INPP4B suppresses the PI3K/AKT signaling pathway and results in reduced tumor growth, which appears to be associated with PTEN24." (PMID 30213980, 2018). "Mechanistically, the “canonical” tumour suppressive mechanism of INPP4B functions through its regulation of Akt-activity." (PMID 29415082, 2018). "We therefore identify INPP4B as an tumor suppressor in PDAC which attenuates AKT activation and participates in preservation of Ecad in endocytic pool and cellular membrane." (PMID 29952716, 2018). "This dephosphorylation compromises the activation of AKT, which unveils the tumor-suppressing function of INPP4B in the context of some malignancies." (PMID 29952716, 2018). "In keeping with its role in limiting pro-survival signaling through AKT, INPP4B was proposed to be a putative tumor suppressor." (PMID 29415082, 2018). "We found that loss of the tumor suppressors PTEN and INPP4B occurred with high frequencies in TNBC PDX, while PIK3CA and AKT1 mutations were rare." (PMID 27374081, 2016). "The tumor suppressive role of INPP4B is linked to its function in dephosphorylating PIP2, depleting this substrate of PI3K, and accordingly loss of INPP4B leads to increased PIP3-mediated signaling to AKT and is associated with poor outcome." (PMID 27484095, 2016). "In particular, a recent study reported a tumour suppressive function for INPP4B in melanocytic neoplasm that was primarily mediated by a small isoform of the protein." (PMID 26573229, 2015). "For example, we isolated inositol polyphosphate 4-phosphatase type II(INPP4B)gene, a known tumor suppressor in breast, prostate, and among other malignancies." (PMID 25962159, 2015). "While PTEN and some 5-phosphatases such as SHIP2 and PIB5PA are tumour suppressors, the 4-phosphatase INPP4B also plays a tumour suppressive role in variety types of cancers." (PMID 26573229, 2015). "The reduced in vivo tumorigenicity in the INPP4B-expressing cells strongly supports the tumor suppressor role of INPP4B in NPC." (PMID 25126743, 2014).
tumor (continued). "Together, we provide evidence from multiple in vitro cell studies and in vivo cre-loxP ERαKO tumor models, as well as human BCa tissue data to prove ERα plays a protective role in BCa initiation and growth via modulating the INPP4B/Akt pathway." (PMID 25277204, 2014). "The transcription of INPP4B was greatly reduced or completely lost in five tumor lines, while its expression was detected in the immortalized nasopharyngeal epithelial cells NP69 and an EBV-ve NPC cell line, HK-1." (PMID 25126743, 2014). "By RT-PCR and Western blotting, we revealed that the expression of INPP4B was down-regulated in all five established EBV-positive tumor lines." (PMID 25126743, 2014). "Despite the limited in vitro effect on cell proliferation and survival, significant suppression was observed in in vivo tumor growth of the cells stably expressing INPP4B." (PMID 25126743, 2014). "We successfully determined the copy number of INPP4B in 176 tumor samples displaying the following distribution; 15% ≤1 copies, 62% 2 copies, and 23% ≥3 copies." (PMID 24500884, 2014). "Expression of INPP4B was established in 172 tumor samples and graded as follows: 47% −, 22% +, and 31% ++." (PMID 24500884, 2014). "For example, knocking down INPP4B resulted in epithelial cell growth and overexpression of INPP4B led to reduced tumor growth, suggesting that INPP4B is a tumor suppressor gene." (PMID 23875016, 2013). "Our findings suggest that INPP4B could be a potential target for enhancing the efficacy of T‐cell‐mediated immune responses against tumours." (PMID 40754682, 2025). "Our results indicate that INPP4B could be a potential target for preventing exhaustion and enhancing the efficacy of T‐cell‐mediated immune responses against tumours." (PMID 40754682, 2025). "Additionally, we observed increased expression levels of INPP4B in exhausted T cells within the tumour microenvironment." (PMID 40754682, 2025). "Additionally, we observe increased expression level of INPP4B in exhausted T cells within the tumour microenvironment." (PMID 40754682, 2025). "Furthermore, using pan‐cancer scRNA‐seq datasets of tumour‐infiltrating T cells, we revealed that INPP4B is upregulated in exhausted T cells within the tumour microenvironment." (PMID 40754682, 2025). "Our findings suggest that INPP4B could be a promising target for enhancing the efficacy of T‐cell‐mediated immune responses against tumours." (PMID 40754682, 2025). "Based on these data, it has been hypothesized that INPP4B may have seemingly contradictory functions as an oncogenic driver or a tumor suppressor depending on the tumor entity, cancer grade, and clinical stage." (PMID 36993823, 2023). "In addition, a significant increase in INPP4B expression was observed in chemotherapy-treated RB tumor patient samples compared to untreated specimen." (PMID 36993823, 2023). "In the study presented, INPP4B overexpression reduced proliferation, viability, and growth of etoposide-resistant RB cell lines and concomitantly increased caspase-3/7 mediated apoptosis levels, supporting INPP4B`s role as a tumor suppressor in RB cells." (PMID 36993823, 2023). "Evaluation of CAM tumors developing from grafted RB cells as well as quantification of tumor weight and size showed that etoposide-resistant, INPP4B overexpressing RB355 cells developed significantly smaller tumors than control cells and likewise exhibited weight." (PMID 36993823, 2023). "Besides, a significant increase in INPP4B expression was observed in chemotherapy-treated RB tumor patient samples compared to untreated tumors." (PMID 36993823, 2023).
tumor (continued). "INPP4B overexpression in etoposide-resistant RB cells resulted in a significant reduction in cell viability with reduced growth, proliferation, anchorage-independent growth, and in ovo tumor formation." (PMID 36993823, 2023). "INPP4B functions as a tumor suppressor in prostate, thyroid or bladder cancer, but as an oncomir in CRC cells where it regulates Akt and GSK3 pathways and downregulates tumor-suppressor PTEN, so its role depends on the cellular context and requires further investigation." (PMID 35163157, 2022). "INPP4B is a tumor suppressor gene that inhibits the PI3K signaling pathway." (PMID 36189258, 2022). "In some tumors, INPP4B acts as a tumor suppressor in similar ways as the protein PTEN." (PMID 36147923, 2022). "The contradictory role of INPP4B in different tumours or the same tumour may reflect its extremely complex function in tumours." (PMID 34729121, 2021). "In addition, the expression of INPP4B protein in tumour tissues was decreased compared with that in normal controls." (PMID 34729121, 2021). "Previous studies suggested that INPP4B is involved in tumour cell apoptosis." (PMID 33879096, 2021). "Proteins that contribute most strongly to proteotype-based classification include inositol polyphosphate-4-phosphatase, type II (INPP4B), cyclin-dependent kinase 1 (CDK1), and receptor tyrosine kinase 2 (ERBB2) are associated with estrogen receptor (ER) status, HER2 status tumor, and grade status." (PMID 34948142, 2021). "INPP4B expression was significantly correlated with TNM tumour stage (I-II vs. III-IV, P=0.033) and histopathological differentiation (high-moderate vs. low-undifferentiated, P=0.019) and weakly related to tumour size (<6 cm vs. ≥6 cm, P=0.08) but not related to any other clinical parameters." (PMID 34729121, 2021). "Both PTEN and INPP4B are widely expressed and function as tumor suppressors in multiple cancers." (PMID 32413098, 2020). "The first evidence characterizing INPP4B as a gene with importance in cancer was from a RNA interference screen in immortalized human mammary epithelial cells (HMEC) designed to identify candidate tumour suppressors." (PMID 31695845, 2019). "Moreover, INPP4B was reported to have both tumour promoting and tumour suppressing features in different subsets of the same cancer." (PMID 31695845, 2019). "In contrast to its reported role in tumor suppression, emerging evidence suggest that high levels of INPP4B may promote the development and progression of some cancers." (PMID 29415082, 2018). "In order to confirm our hypothesis that INPP4B acted as a tumor suppressor in PDAC cells through rectifying PI3K/AKT signaling, phosphorylation status of AKT was tested in Ad-INPP4B and INPP4B-Rnai group by western blot." (PMID 29952716, 2018). "IHC staining verified the presence of INPP4B in the tumours with HeLa‐INPP4B injection." (PMID 29516642, 2018). "INPP4B is initially identified as a tumor suppressor due to its negatively regulatory effects on PI3K/AKT pathway which outlines a network that steers important biological processes such as cell adhesion and migration, all of which are disrupted in several types of cancers." (PMID 29952716, 2018). "INPP4B expression is altered in human cancers and the phosphatase appears to play both oncogenic and tumour suppressor roles depending on whether expression is increased or decreased." (PMID 28082369, 2017). "Consequently, Inpp4b−/− mice were crossed with Pten+/− mice to examine the co-operative tumour suppressor function of INPP4B in the context of PTEN haploinsufficiency." (PMID 28082369, 2017). "Therefore, despite INPP4B tumour suppressor function being reported in vivo and in vitro in various cancers, there is emerging evidence that INPP4B also plays a paradoxical oncogenic role in certain other cancer contexts." (PMID 28082369, 2017).
tumor (continued). "Moreover, PIP3 levels seem to be also tightly modulated by another tumor suppressor, inositol polyphosphate 4-phosphatase type II (INPP4B), which dephosphorylates PIP3 to PIP2." (PMID 27474173, 2016). "Adopting a similar approach for INPP4B-deficient tumors may broaden the window of therapeutic applications for PARP inhibitors in a greater selection of tumors and establish INPP4B as a tumor biomarker." (PMID 25868852, 2015). "Notably, the downregulation of INPP4B was commonly found in both the tumor lines and primary tumors." (PMID 25126743, 2014). "In addition, recent evidence indicates that the inositol polyphosphate 4-phosphatase type II (INPP4B) is an important tumor suppressor of the PI3K pathway 4–6." (PMID 24500884, 2014). "Likewise, the expression of a putative tumor suppressor, INPP4B, is frequently lost in breast cancer, and is reported to be associated with decreased patient survival." (PMID 25542038, 2014). "In vivo growth inhibition was clearly demonstrated in the tumor cells stably expressing INPP4B." (PMID 25126743, 2014). "For INPP4B expression, we found no the significant impact on the response, although high expression was associated with worse prognostic factors, such as large tumor size and high nuclear grade." (PMID 25542038, 2014). "Recent evidence indicates that INPP4B is an important tumor suppressor of the PI3K pathway 4–6,19." (PMID 24500884, 2014). "Increasing evidence has confirmed that INPP4B is a tumor suppressor gene." (PMID 22121480, 2012). "Furthermore, INPP4B knockdown in ER-positive breast cancer cells increased Akt activation, cell proliferation, and xenograft tumor growth." (PMID 22121480, 2012). "Additionally, a subset of the highly significant regulated genes may be functionally involved in INPP4B-mediated effects on apoptosis and cell growth in vitro and therefore involved in etoposide-resistant RB tumor progression in vivo." (PMID 36993823, 2023). "However, recent studies have contradicted this function and showed that INPP4B could promote tumor growth." (PMID 36147923, 2022). "Thus, combined with previous findings in other tumors, our experiments demonstrate a tumor-specific effect of INPP4B, which may either inhibit or promote tumor progression through different pathways." (PMID 36147923, 2022). "Thus, INPP4B is anticipated to act as a tumor suppressor by antagonizing PI3K/Akt signaling." (PMID 35070988, 2021). "In addition, high INPP4B expression in GC patients with large tumour size/low-undifferentiated/TNM's III-IV stage was correlated with a poor prognosis but it was correlated with a better prognosis in patients with small tumour size/high-moderate differentiated/TNM's I-II stage patients." (PMID 34729121, 2021). "However, unlike PTEN, the underlying molecular mechanisms by which INPP4B exerts its tumour suppressive function are poorly understood." (PMID 34729121, 2021). "In addition, overexpression of INPP4B decreased xenograft tumour growth in nude mice." (PMID 29516642, 2018). "In addition, INPP4B expression significantly prevented tumour growth in mice in vivo." (PMID 29516642, 2018). "Thus, the loss of INPP4B expression in human epithelial cells leads to constitutive association of AKT-PH domain with the plasma membrane, increased AKT activation and enhances tumor formation." (PMID 25126743, 2014). "Importantly and notably, INPP4B has been demonstrated as a tumor suppressor in different cancer types such as prostate and breast, consistent with what we have observed for BCa using IHC staining of the INPP4B protein." (PMID 25277204, 2014). "INPP4B functions as a regulator of the PI3K-AKT signaling pathway and exhibits tumor suppressive or oncogenic activity in a cancer type-specific manner." (PMID 41008874, 2025). "The INPP4B and PTEN tumor suppressors are lost in advanced disease in 47% and 42% of cancers, respectively." (PMID 38001678, 2023).
tumor (continued). "Tumor suppressors, such as phosphatase and tensin homolog (PTEN) and inositol polyphosphate 4-phosphatase type II (INPP4B), are involved in dephosphorylation of PIP3 to PIP2, therefore suppressing the activity of Akt and its downstream effectors." (PMID 37958470, 2023). "INPP4B has been reported as a negative regulator of PI3K/AKT signaling and was anticipated to act as a tumor suppressor by inhibiting this pathway." (PMID 36993823, 2023). "INPP4B is a potential tumor suppressor gene; the main function of INPP4B is to inhibit the activation of the PI3K/AKT pathway, and thereby, the proliferation and survival of tumor cells." (PMID 36147923, 2022). "It was discovered that a molecular downstream target for miR-1290 is inositol polyphosphatase-4 phosphatase type II (INPP4B), a member of the PI3K/Akt signaling pathway which plays a key role in the initiation and progression of the tumor." (PMID 35163157, 2022). "The tumor suppressors PTEN and INPP4B are negative regulators of AKT as they catalyze the dephosphorylation of PIP3 to PIP2, limiting the activation of the PI3K signaling axis." (PMID 35565291, 2022). "We and others have identified that INPP4B inhibits AKT signaling and exhibits tumor suppressor activity in triple-negative (ER−/PR−/HER2−) and basal-like breast cancers." (PMID 34035258, 2021). "INPP4B, like PTEN, is anticipated to act as a tumour suppressor by antagonizing PI3K-Akt signalling." (PMID 34729121, 2021). "Among them, DPY30, EREG, PLA2G16, ZNF185, PADI1, INPP4B and AP1S3 have been reported to be involved in tumor genesis and progression, and they were significantly positively correlated with risk score." (PMID 34090418, 2021). "Genes of interest involved in tumor progression or uterine fibroids, from previous studies, FGFR1, CCND1, PCDH11X, VDR, NDRG2 and INPP4B, are indicated in the volcano plot." (PMID 33807176, 2021). "In the small tumour size (<6 cm) group, high-moderate differentiation group and TNM early stage (I-II) group, INPP4B+ GC patients seems to have a longer OS than INPP4B- GC patients (respectively)." (PMID 34729121, 2021). "INPP4B negatively regulates the PI3K-Akt signalling pathway, which is expressed at low levels and has a tumour-suppressive role in several types of human malignancies 13-15." (PMID 34729121, 2021). "What makes us wonder is that INPP4B knockdown in BGC823 cells can lead to the activation of p-Akt, a typical role of tumour suppressors, but the phenotypic experiment suggested it functioned like an oncogene, which seems to be contradictory." (PMID 34729121, 2021). "Our study provided genetic evidence of interactions between INPP4B and RAD50, and deepened our understandings on the orchestrated genetic machinery governing tumor progression." (PMID 31872854, 2020). "AKT is inhibited by tumor suppressors including phosphatase and tensin homolog (PTEN) and inositol polyphosphate 4-phosphatase type II (INPP4B)." (PMID 32395722, 2020). "This analysis confirmed the connection of INPP4B with ER status, CDK1 with tumor grade, and ERBB2 with HER2 status." (PMID 31315058, 2019). "Abundance of our three key proteins INPP4B, CDK1, and ERBB2 across tumors of different ER status, tumor grade, and HER2 status correlated well with their respective transcript levels." (PMID 31315058, 2019). "INPP4B is involved in the phosphatidylinositol signaling pathway, which inhibits PI3K/Akt signaling and is emerging as a tumor suppressor in a variety of tissues." (PMID 31662781, 2019). "AKT is inhibited by tumor suppressors including PTEN and inositol polyphosphate 4-phosphatase type II (INPP4B)." (PMID 31284467, 2019). "In particular, the INPP4B gene, identified as a biomarker of LIHC by G2Vec, has been studied as a tumor suppressor in various cancer types, such as breast, ovary, and prostate cancers." (PMID 30213980, 2018).